MMP9 (matrix metallopeptidase 9)
Diseases named in the same sentence as MMP9 in open-access papers (continued):
Sharing a sentence is not in itself a finding about the gene and the disease.
lung carcinoma (continued). "Both ABL knockdown and treatment of lung cancer cells with ABL-specific allosteric inhibitors markedly reduced MMP9 secretion and gelatinase activity." (PMID 33119681, 2020). "We selected the representative markers of tissue invasion and metastasis, MMP-2 and MMP-9 up-regulate lung cancer migration under microgravity conditions." (PMID 31601869, 2019). "Higher levels and activity of MMP2 and MMP9 have a significant association with the TNM stage of lung cancer and poor clinical evolution of patients with lung cancer." (PMID 30867003, 2019). "Similar effect was observed by Sun et al52 who showed that MiR‐329 caused down‐regulation of MET expression what led to decreased mRNA level of MMP‐7 and MMP‐9 and thus reduced cellular migration and invasiveness of lung cancer cells." (PMID 31638339, 2019). "Further analysis showed that lung cancer cells’ interaction with SDF-1 mediated the upregulation of MMP9 expression which further increased lung cancer cell chemoinvasion to bone." (PMID 31330786, 2019). "Particularly, CD11b+CD33+HLA-DR- MDSCs significantly increase in lung cancer patients after thoracotomy, and are more efficient in secreting MMP-9, promoting angiogenesis and tumor growth than MDSCs isolated before surgical operation in allograft tumor model." (PMID 31477121, 2019). "MDM2 and matrix metalloproteinase 9 (MMP9) expressions are related to the formation and migration of lung cancer; therefore, they can serve as the markers for the treatment and prognosis of the disease." (PMID 31885751, 2019). "This study demonstrated that inhibition of PKCα/NOX-2/ROS/ATF2 signaling pathway decreases expression of MMP-9, suggesting one of the mechanisms of anti-invasive effect by curcumin in lung cancer cells." (PMID 31817718, 2019). "Our observations are in agreement with a study in lung cancer concluding that an increase in MMP9 levels after three cycles of chemotherapy was predictive for progression with 5% increase in the odds of progression for an increase of 10 ng of MMP9." (PMID 31191742, 2019). "ALDOA (aldolase, fructose-bisphosphate A), one of the NRF2-regulated genes identified in our ChIP-Seq results, promotes the metastasis of lung cancer by activating the HIF-1α/MMP9 axis." (PMID 31884422, 2019). "In order to address the functional relevance of the induction of metalloprotease genes by PKCα in lung cancer cells, we determined MMP-9 activity by zymography, using conditioned medium collected from A549 cells treated with either PMA or AJH-836." (PMID 30988374, 2019). "In a lung cancer study, comparing expression of MMP9 in normal vs. cancer tissue MMP9 expression was the highest in adenocarcinoma of greater tumor stage (III and IV)." (PMID 31191742, 2019). "Positive correlations between AQP3, MMP2, and MMP9 and cancer invasiveness also occur in lung cancer." (PMID 29922644, 2018). "Fibulin-3 has been shown to regulate MMP-9 expression and activity in lung cancer and malignant glioma." (PMID 30046386, 2018). "In lung cancer cells, migration was facilitated by AQP1 expression, linked to expression of MMP2 and MMP9." (PMID 29922644, 2018). "MMP-2 and -9; gelatinases, are very closely associated with the metastatic properties of lung cancer, which suggests that creating potent MMP-2 and MMP-9 inhibitors should be an important goal in lung cancer therapy." (PMID 29679218, 2018). "SLIT3 was also induced by a DNA methylation inhibitor, and silencing of SLIT3 promoted proliferation, migration, and invasion with enhanced expression of MMP2 and MMP9 in lung cancer cells." (PMID 30613364, 2018). "Matrix metalloproteinase activation has been described in large cell lung carcinoma, where elevated CAV1 expression correlates with advanced stages of lung cancer as well as increased MMP9/MMP2 expression and activity." (PMID 29340103, 2017). "The upregulation of MMP-2 and MMP-9 is one of the mechanisms through which Skp2 promotes lung cancer cell invasion." (PMID 29207614, 2017).
lung carcinoma (continued). "MMP-9 is one of the most studied MMPs in lung cancer, with several reports addressing its potential as diagnostic marker." (PMID 29207990, 2017). "MMP family of proteinases, particularly MMP-1, MMP-2 and MMP-9 expressed in lung cancer, play an important role in malignant tumor metastasis." (PMID 28915603, 2017). "MMP9 displayed protective function in chronic kidney disease, lung cancer and systemic autoimmune disease (lymphoproliferation and lupus)." (PMID 27861153, 2017). "An oncolytic adenovirus expressing the collagenase matrix metalloproteinase 9 (MMP)-9 has also demonstrated improved viral spread in human pancreatic and lung cancer xenograft models." (PMID 29157300, 2017). "Our study highlights the important role of the S100A4/NF-κB/MMP9 signaling axis in promoting lung cancer invasive capacity, and demonstrates that S100A4 overexpression associates with reduced overall survival among patients with lung adenocarcinoma." (PMID 27127879, 2016). "Collectively, this study highlights the importance of the S100A4/NF-κB/MMP9 axis in lung cancer invasion and provides a rationale for targeting S100A4 to combat lung cancer." (PMID 27127879, 2016). "SR-A1 suppresses lung cancer progression by inhibiting MMP-9 production and modulates macrophage polarization in cardiovascular inflammatory microenvironments." (PMID 27367025, 2016). "In support of our study, recent work has shown that both S100A4 and MMP9 are upregulated in patient-derived lung cancer tissues and positively correlate with each other, further implicating the importance of S100A4/MMP9 signaling in lung cancer progression." (PMID 27127879, 2016). "Using siRNA knockdown, we confirmed that JunD downregulation decreased expression of cyclin D1, cyclin E and MMP9 in lung cancer cells." (PMID 27184257, 2016). "Our study extends current understanding by showing that at physiologically achievable levels, niclosamide can effectively target the S100A4/NF-κB/MMP9 signaling axis in lung cancer by decreasing S100A4 expression." (PMID 27127879, 2016). "We examined the effects of SIRT6 expression on the ERK1/2/MMP9 pathway, which is involved in lung cancer metastasis and invasion." (PMID 27777384, 2016). "Compared to HD, a decrease in IL-8 (~8.1 folds; P < 0.0001) but an increase in MMP-9 (~1.6 folds; P < 0.05) levels were observed in the lung cancer patients." (PMID 27811960, 2016). "The reduced spreading effect and cell motility caused by miR-326 in lung cancer cells was revealed to be associated with the inhibition of the protein expression of cell migration and invasion molecules MMP-7 and MMP-9." (PMID 26840018, 2016). "For instance, it was demonstrated that curcumin inhibited lung cancer cells invasion by modulating the PKCα/Nox-2/ROS/ATF-2 signaling pathway leading to downregulation of MMP-9 expression." (PMID 27834913, 2016). "Resveratrol suppressed NF-κB activity leading to inhibition of HO-1 and subsequently downregulating the expression of MMP-2 and MMP-9 in lung cancer cells." (PMID 27834913, 2016). "Fibronectin is known to induce activation of FAK via extracellular signal-regulated kinase (ERK) or PI3K/Akt to increase matrix metalloproteinase (MMP)-9/calpain-2 or MMP-9/RhoA activity, respectively, and lead to lung cancer metastasis." (PMID 26517522, 2016). "Collectively, these results implicate S100A4 in driving lung cancer invasive potential, at least in part, through activation of the NF-κB/MMP9 axis." (PMID 27127879, 2016). "EFEMP1 is associated with decreased MMP-2 and MMP-7 levels in lung cancer and MMP-2 and MMP-9 levels in endometrial carcinoma, which are also observed in highly metastasizing and rapidly expanding tumors." (PMID 25987128, 2015). "By utilizing a combination of PAI-2 and MMP-9, more precise prognostic information than merely using pathological stage alone can be obtained for lung cancer patients." (PMID 26230665, 2015).
lung carcinoma (continued). "We conducted a meta-analysis, using a comprehensive strategy based on the logistic regression and a model-free approach, to derive a more precise estimation of the relationship between MMP1, MMP2, MMP9 and MMP13 polymorphisms with lung cancer risk." (PMID 26198673, 2015). "This seems in to be consistent with our recent study on lung cancer, in which WA-25 potently inhibited MMP-9 expression in human A549 and murine Lewis lung carcinoma cells, thereby suppressing lung cancer growth in animal models." (PMID 25668036, 2015). "MMP-9 mRNA expression levels in lymphocytes tended to be higher in malignant pleural effusions of lung cancer when compared with healthy pleural effusions." (PMID 25621068, 2015). "On the basis of our results, fucoidan is able to mediate the activities of MMP-2 and MMP-9, also in line with the report that fucoidan suppressed migration and invasion of A549 lung cancer cells by suppressing secretion and/or expression of MMP-2." (PMID 25854641, 2015). "While expression of MMP-2 and MMP-9 have been characterized extensively in lung cancer, much less is known about MMP-13." (PMID 26193700, 2015). "E2F1 is a transcriptional activator of MMP-9 that regulates lung cancer cell invasion and metastasis." (PMID 25009665, 2014). "Conversely, it has been demonstrated that MMP-9 is an independent adverse prognostic factor in the tissues and serum of lung cancer." (PMID 24396477, 2014). "This study aimed to determine the effect of andrographolide (AD) on the growth of H3255 lung cancer cells and its possible impact on the expression and activity of the matrix metalloproteinase (MMP)-9 protein." (PMID 24137258, 2013). "Regulation of MMP-9 activity by Akt or ERK controls FAK-activated lung cancer metastasis; furthermore, ERK-CK2-mediated phosphorylation of α-catenin promotes β-catenin transactivation and tumor cell invasion." (PMID 24023938, 2013). "Previous studies have indicated that NF-κB is important in the PMA-induced expression of MMP-9 in lung cancer." (PMID 24137258, 2013). "HPV 16 E6 up-regulates pro-angiogenic MMP-2 and MMP-9 through inducing IL-8 expression in lung cancer cells." (PMID 23349885, 2013). "For example, genetic aberrations in genes for matrix metalloproteinase (MMP) -3 and MMP-9 or the x-ray repair protein XRCC1 have been reported to influence the clinical behavior and risk of metastasis of lung cancer." (PMID 23840350, 2013). "The gene expression level of MMP-9, however, was lower in lung cancer specimens compared to the other two groups." (PMID 22593690, 2012). "The main aim of this study was to investigate the relationship between 3 functional polymorphisms in the regulatory regions of the human gelatinases MMP2 and MMP9 and the human stromelysin MMP3 and lung cancer risk in the individuals from the CAPUA study." (PMID 22455335, 2012). "To investigate enzymatic activity of secreted MMP-9 by zymography, we infected A549 lung carcinoma cells with either GLV-1h68 or GLV-1h255." (PMID 22917220, 2012). "We evaluated the effect of three polymorphisms in the promoter regions of two human gelatinases, MMP2 and MMP9, and the human stromelysin MMP3 on the risk and survival time of lung cancer." (PMID 22455335, 2012). "Knock-down of c-Myc in a murine lung cancer model led to a reduction in MMP-9 levels and diminished metastasis of lung tumor cells to distant sites." (PMID 22226054, 2012). "High serum MMP-9 levels have been shown to correlate with poor survival in patients with lung cancer." (PMID 23028922, 2012). "In the present study, we showed that TGase 2 down-regulation in lung cancer cells inhibited their invasive and migratory properties via the regulation of MMP-9." (PMID 21943122, 2011). "Similarly, IL-7 enhances bladder cancer invasion through NF-κB-mediated MMP-9 expression and promotes lung cancer proliferation by upregulating cyclin D1 via the c-FOS/c-Jun pathway." (PMID 41596598, 2026).
lung carcinoma (continued). "In addition, HK suppressed the migration and invasion of H1299 lung cancer cells by disrupting the expression of matrix metalloproteinase 9 (MMP9) through HDAC6 modulation." (PMID 41296425, 2025). "Moreover, the effects of circDENND4C, miR-200b, and MMP-9 in lung cancer have also been investigated separately." (PMID 40034591, 2025). "Hence, further research is still needed to clarify the whole regulatory networks of circDENND4C and its downstream miR-200b and MMP-9 during the pathogenesis of lung cancer." (PMID 40034591, 2025). "Similarly suppression of BMP-1 expression reduces the activity of TGF-β, downregulates MMP2/MMP9 expression and decreases the invasion of lung cancer cells." (PMID 39792296, 2025). "Thus, we can draw a key conclusion that circDENND4C accelerated lung cancer progression, and this effect was related to the miR-200b/MMP-9 axis." (PMID 40034591, 2025). "Mechanistically, ADAR1 may promote proliferation, invasion, migration, and tumorigenesis in lung cancer cells via the ERK/c-FOS/MMP-9 axis." (PMID 41309247, 2025). "Hence, our data implied that the circDENND4C/miR-200b/MMP-9 regulatory axis was shown to modulate the tight and adhesion junctions to control the metastasis of lung cancer cells." (PMID 40034591, 2025). "For instance, circDENND4C was found to promote proliferation and metastasis of lung cancer, miR-200b was also discovered to inhibit tumor growth and chemoresistance in lung cancer, and MMP-9 was further disclosed to potentiate lung cancer cell migration and invasion." (PMID 40034591, 2025). "However, from the results of our study, the role of the circDENND4C/miR-200b/MMP-9 regulatory axis in the progression of lung cancer cannot be ignored." (PMID 40034591, 2025). "Similarly, Skp2 also increases the expression of MMP-2 and MMP-9 to promote invasion of lung cancer cells." (PMID 41385185, 2025). "Notably, the role of MMP-9 and MMP-2 in the development of brain metastases is of particular interest, given that BM is a leading cause of death in lung cancer patients." (PMID 40321254, 2025). "On the other hand, oral administration of chia extracts for five months significantly reduced lung cancer biomarkers, including the relative weight of the lung, ICAM-1, c-MYC, and MMP9 gene expression, and lung histology was improved considerably compared to the lung cancer control one." (PMID 39338293, 2024). "In addition, C35 possessed a significant inhibition of migration by reducing the expression of matrix metalloproteinases-2 (MMP-2) and MMP-9 in lung cancer cells." (PMID 38776295, 2024). "Therefore, the protein expression of MMP-2 and MMP-9 in lung cancer cells in response to C35 treatment were evaluated through Western blot and ELISA." (PMID 38776295, 2024). "Moreover, dieckol reduces migration and invasion of lung cancer cells by decreasing matrix metalloproteinase-9 (MMP-9) and increasing E-cadherin levels." (PMID 37760037, 2023). "We therefore conclude that BARX1 transactivates CDC20, CDC45, TRIM37 and MMP-9 genes, thereby promoting cellular proliferation, migration and invasion of lung cancer cells due to the functional roles of these genes in cell-cycle progression, DNA synthesis and their association with carcinogenesis." (PMID 37587140, 2023). "This miRNA suppresses MMP-9 expression and metastatic characteristics of A549 lung cancer cells." (PMID 38069210, 2023). "Also, CCR2 inhibitor can suppress CCL2-mediated lung cancer cell invasion by downregulating MMP-9 expression." (PMID 37325423, 2023). "Specific genotypes affect MMP-2 and MMP-9 concentrations in both lung cancer patients and healthy controls, which may thereby increase lung cancer risk, disease aggressiveness, and patient survival outcomes." (PMID 37445754, 2023). "However, the number of published genotypic articles on the role of MMP-2 and MMP-9 in lung cancer has been extremely low in the preceding decade." (PMID 37445754, 2023).
lung carcinoma (continued). "Previous studies of our group showed that MMP2 and MMP9 were major MMPs secreted by murine tumor cells derived from Lewis lung cancer cells by gelatin zymography and affinity chromatography demonstrated that these MMPs were bound by EGCG immobilized on agarose gel." (PMID 36677584, 2023). "In pancreatic and lung cancers, NETs were found to contain the matrix metallopeptidase 9 (MMP-9), a known accelerator of angiogenesis through the degradation of extracellular matrix by activated neutrophils which triggers vascular endothelial growth factor (VEGF) release." (PMID 37143649, 2023). "The excessive expression of MMP-2 and MMP-9 is also highly correlated with lung cancer metastasis." (PMID 35711540, 2022). "They prevent the association of MMP9 with its receptors (α4β1 integrin/CD44), resulting in the blocking of a downstream signalling pathway required for MMP9-mediated tumour cell migration in vitro and the inhibition of tumour metastasis in xenograft mouse models of lung cancer." (PMID 35158891, 2022). "In this study, ART suppressed the protein expressions of HuR and MMP-9, indicating that it may inhibit the proliferation, migration and invasion but promote the apoptosis of human lung cancer A549 cells by regulating the expressions of HuR and MMP-9." (PMID 35361045, 2022). "It is worth noting that moderate intensity constant load exercise can also reduce the level of MMP9 in lung cancer tissues, which may control tumor metastasis to a certain extent." (PMID 35371324, 2022). "Additionally, the mRNA expression and protein levels of Snail, MMP2, and MMP9 are decreasing in lung cancer cells treated by rhein." (PMID 35178453, 2022). "Addressing the mechanism of how MSCs directly affect the behavior of lung cancer cells was revealed when bone marrow-derived MSCs were shown to promote metastasis through activation of the tyrosine-protein kinase ABL-matrix metalloproteinase 9 (MMP9) signaling axis in a panel of lung cancer cells." (PMID 34572864, 2021). "Moreover, recently, the downregulation of MMP9 in the A549 lung cancer cell line transfected with miR-145 has been reported, suggesting that miR-145 replacement in lung cancer can be used to suppress the tumor metastasis." (PMID 34307654, 2021). "Our results clearly highlight the importance of MMP9, of the two MMPs, in regulating the levels of proBDNF and mBDNF in lung cancer cell media and might be, in part, explained by previous reports showing that MMP2 is not able to convert proBDNF to Mbdnf." (PMID 34209215, 2021). "Similarly, exosomes derived from lung CSCs promote EMT, migration, and invasion of lung cancer cells by upregulating the expression levels of N-cadherin, Vimentin, MMP-9, and MMP-1, and downregulating the expression of E-cadherin." (PMID 34511114, 2021). "Tumor-derived exosomes derived from lung cancer cells promote the invasion and migration of lung cancer cells by regulating the expression levels of specific genes, including those encoding the matrix metalloproteinases MMP-2, MMP-9, PTEN, E-cadherin, and ROCK1." (PMID 34511114, 2021). "Thus, we evaluated the protein levels of the lung cancer metastasis-related factors, including MMP-9." (PMID 33800298, 2021).